SSX9P (SSX family member 9, pseudogene)
Description:
Could act as a modulator of transcription.
Synonyms: formerly SSX9
Gene: Transcribed unprocessed pseudogene on chromosome X (48,296,816 to 48,304,867, reverse strand). Ensembl gene ENSG00000204648.